MYD88 (MYD88 innate immune signal transduction adaptor)
Diseases named in the same sentence as MYD88 in open-access papers (continued):
Sharing a sentence is not in itself a finding about the gene and the disease.
infection (continued). "In addition, the functional effects of UL88 in preventing spread likely stem from inhibition of the MyD88-mediated production of a soluble mediator(s) that can confer greater resistance against virus spread to neighboring cells, a phenotype that is functionally irrelevant in a high MOI infection." (PMID 40638072, 2025). "However, the majority of antiviral ISGs, including OAS1, MX2, IFI6, IFITM1, IFI27, and IFTM2, were downregulated in cells transduced with MyD88 (in the presence or absence of infection) and were also downregulated in cells infected with UL88-deficient HCMV vs wild-type HCMV." (PMID 40638072, 2025). "However, we do not anticipate major differences between myd88−/− and WT zebrafish in the absence of an insult (injury or infection) that could trigger MyD88 pathway activation." (PMID 39271818, 2024). "Moreover, EgP stimulates the TLR2/MyD88/NF-κB signaling pathway, resulting in the synthesis of α-SMA and Collagen I. The data suggest that infection with E. granulosus may stimulate the production of IL-9 through the activation of the TLR2/MyD88/NF-κB signaling pathway, which is mediated by TLR2." (PMID 39199394, 2024). "Thus, F. tularensis may antagonize MYD88 to block both TLR and IL-1R signaling during infection." (PMID 37404047, 2023). "Although this mechanism may not be the only cause of inflammation-induced cancer, this result indicates that MYD88 has a cell-intrinsic tumour-initiating activity and that the constitutive infection of microbes is sufficient for oncogenesis in the absence of immune cells." (PMID 33597599, 2021). "Moreover, mice lacking MyD88, a major adapter molecule required for downstream signaling events by the majority of TLR/IL-1R family members, demonstrate enhanced susceptibility to aerosol infection with M.tb." (PMID 33444288, 2021). "In line with the mRNA expression of inflammatory cytokines, cells lacking MyD88 were not able to degrade IκB-α, the inhibitor of the transcription factor nuclear factor ‘kappa-light-chain-enhancer’ of activated B-cells (NF-κB), upon infection with either C. acnes or L.m.." (PMID 33178195, 2020). "Similarly, mice lacking MyD88 are also more susceptible to PR8, H5N1 and pH1N1 infection." (PMID 32260457, 2020). "Furthermore, animal infection models and vaccination studies in humans have shown that females have increased expression of several molecules involved in the TLR pathway and Th1 responses, including TLR8, myeloid differentiation primary response 88 (MyD88), and nuclear factor-kappaB (NFκB)." (PMID 30756088, 2019). "This study revealed that LEP and DPEP could down-regulate the activity of NF-κB p65 by regulating MyD88-dependent signaling pathways of TLR4 and TLR7, thereby exerting their antiviral effects, and the treatment effects might be more significant in the early phase of infection." (PMID 31551774, 2019). "Furthermore, we observed high bacterial loads in the feces and the liver of Rorc-MyDON mice, overall confirming that ILC3- and T cell-restricted functional MyD88 expression is not sufficient to induce an appropriate host response to infection with C. rodentium." (PMID 28520792, 2017). "We next hypothesized that factors known to prime cells responding to infection, such as IFN-γ and Granulocyte-Macrophage Colony-Stimulating Factor (GM-CSF), may contribute to the ability of P. gingivalis to induce TLR2-dependent, MyD88-independent inflammatory signaling." (PMID 28848717, 2017). "However, the significance of MyD88-mediated signaling in specific intestinal immune and nonimmune cell types for the activation of the early innate, adaptive and epithelial host responses upon infection remains poorly understood." (PMID 28520792, 2017).
infection (continued). "In addition, MyD88−/− mice developed substantial numbers of intestinal granulomas around the site of infection, which were not seen in MyD88-sufficient C57BL/6 mice, nor when signaling through the adapter protein TRIF (TIR domain–containing adapter–inducing IFN-β adapter protein) was also ablated." (PMID 25114104, 2014). "Thus, signaling through individual TLRs contributes differentially to Treg proportions and CD103 expression levels following infection, resulting in no overall differences in Treg phenotype from wild-type C57BL/6 mice when TLR signaling is ablated in MyD88-deficient mice." (PMID 25114104, 2014). "As MyD88 is critical for control of L. pneumophila replication during in vivo infection but deletion of an individual MyD88-dependent TLR or a combination of TLRs does not recapitulate MyD88 deficiency, it is likely that other MyD88-dependent receptors, including the IL-1R, may play a role." (PMID 23762026, 2013). "However, iNOS−/−, NLRP3−/− and caspase-1−/− mice do not succumb to infection, unlike MyD88−/− mice." (PMID 24098823, 2013). "Since heightened inflammatory mediator release was evident in brain abscess homogenates but not purified immune cell populations at 24 h post-infection, this suggests MyD88-independent contributions from alternative cell types, the identity of which remains unknown at the present time." (PMID 21496301, 2011). "Although there is evidence that TLR-2 may play a regulatory role during infection with L. braziliensis and downregulate DC IL-12 production, all other studies implicate TLRs and TLR-4 ligation and MyD88 signalling in particular in the generation of protection against infection." (PMID 21664694, 2011). "However, infection of pDCs from TLR7−/− or MyD88−/− mice resulted in no cytokine production." (PMID 20661430, 2010). "MyD88 is rapidly and robustly upregulated following exposure to HCMV, irrespective of viral gene expression and, even after infection, primarily within uninfected cells in a culture." (PMID 40638072, 2025). "Specifically, this protective response is dependent on MyD88 and partially dependent on CCR2 and is not specific to the microorganism used during the initial infection." (PMID 40558085, 2025). "Therefore, the biologically relevant factor released from HCMV-infected MyD88-transduced cells is not released in sufficient quantity to be active until d6 post-infection, and this soluble factor requires an extended time period of exposure (>3 d) during an infection to be effective." (PMID 40638072, 2025). "We also observed that the mRNA transcript levels of MyD88 and other proteins in the MyD88 signaling pathway (TIRAP, TRAM, TRIF, and TRAF6, not shown) are similar after low MOI infection with WT TB40/E or UL88-STOP virus." (PMID 40638072, 2025). "Taken together, MyD88 signalling does not play a crucial role or may be redundant in the control of the innate immune response to L. pneumophila infection of zebrafish larvae, suggesting that zebrafish infection mirrors human infection better than the mouse model." (PMID 37155695, 2023). "qRT-PCR analysis of PEC derived from those mice revealed that MAVS-/-IFNAR-/- did not induce any IL-36γ mRNA upon RVFV cl13 infection while IFNAR-/- and MyD88-/-IFNAR-/- showed high levels of IL-36γ mRNA." (PMID 37720217, 2023). "When myd88-/- larvae or WT larvae were injected with ΔdotA-GFP, infection was not established and the bacterial burden decreased over time, indicating that bacteria were cleared." (PMID 37155695, 2023). "In the RSV murine infection model, genetic deletion of MyD88 and TRIF (Myd88/Trif -/-) does not affect viral control and disease progression, in contrast to what happens in Mavs-/- mice." (PMID 35108347, 2022). "The MyD88-activating agonist CpG (TLR9 agonist), but not TRIF-activating Poly I:C (TLR3 agonist), protects against infection in a macrophage-dependent manner." (PMID 36439136, 2022).
infection (continued). "We establish that MyD88-dependent, but not TRIF-dependent, signaling in macrophages is an essential driver of TLR-mediated trained immunity and resistance to infection." (PMID 36439136, 2022). "In contrast, restricting MyD88 signaling to several other cell types, including macrophages, T cells, or ILC3, did not induce efficient intestinal immune responses upon infection." (PMID 34840990, 2021). "After infection with E. chaffeensis, MIP-2 (CXCL2) and TNF mRNA induction in murine bone marrow derived macrophages was MyD88-dependent, but did not require TLR2 or TLR4." (PMID 33747981, 2021). "Myd88−/− and DKO mice had significantly higher levels of Lactobacillales upon infection with H. felis, while WT and TrifLp2 mice did not." (PMID 33477306, 2021). "In contrast, iNOS mRNA was not up-regulated upon infection or LPS-stimulation in TLR-5-fold-/-, MyD88-/- and MyD88-/- TRIF-/- Hoxb8 neutrophils compared to the respective uninfected or unstimulated control cells." (PMID 33747981, 2021). "Interestingly, the gene expressions of certain signal proteins, such as TLR7, MyD88, MDA5, MHCII, and Fc receptor, decreased in HD11 cells and PBMCs-Mφ at 12 hpi, respectively, indicating that IBV could inhibit the immune regulatory function of macrophages at the early stage of its infection." (PMID 33509253, 2021). "These interactions are modulated by TLR2 and MyD88 signaling, but not by TLR4 engagement, after intranasal or intradermal LVS infection." (PMID 32745117, 2020). "In contrast, infection neither affected expression of key activators of the TLR pathway (IRAK1, MYD88, and RELA) nor RELB, a key element pivotal for DC differentiation, maturation, and MHC Class I-restricted presentation." (PMID 32582184, 2020). "Canonical pathway analysis (ReactomePA) revealed that whereas infection with isolate 4I2 activated PRR-related pathways, such as TLRs, NLRs, and MyD88 or TRIF cascades, infection with 6C4 did not." (PMID 32327653, 2020). "Early after infection, at 4 h, comparable levels of NMII genome equivalents (GE) per macrophage were found by qPCR, indicating that MyD88 is not controlling the uptake or early killing of NMII." (PMID 30800124, 2019). "In the absence of the TLR adapter protein MyD88, bacterial induction of Tnfa is lost, demonstrating the central role of TLR pathways in post-infection Tnfa induction." (PMID 31611882, 2019). "To do this, we analyzed MyD88, TRAF6, IKKα, IKKβ, and phospho-IKKα/β (p-IKKα/β), which we found were not affected by infection, and LPS-induced IκBα degradation." (PMID 29440572, 2018). "The elimination of MyD88 in cardiomyocytes determined a lower increase in CCL5, IFNγ and TNFα gene transcription during acute infection by T. cruzi parasites of the Y strain, but it did not significantly modify heart leukocyte infiltration and parasitism." (PMID 30067739, 2018). "Furthermore, an absence of MyD88 in mice has been shown to enhance the infectivity of a strain of the spirochaete Borrelia burgdorferi when transmitted to I. scapularis ticks during feeding, suggesting that a lack of expression of this gene enabled an enhancement of infection within tick cells." (PMID 28202075, 2017). "However, despite the key role of MyD88 in governing intestinal immunity, a thorough understanding of the cell type-specific impact of MyD88 in the activation of the different innate and adaptive intestinal immune responses upon infection has been lacking so far." (PMID 28520792, 2017). "Consistent with previous in vivo data, IOE infection enhanced expression of IRF7 and IFNβ in WT-BMM, but not in MyD88-/- BMM." (PMID 29049365, 2017). "Upon infection, there was a strong and significant increase in the numbers of total and anti-MCMV CD8 T cells in all of the three mouse strains expressing MyD88 and/or Ly49H, but not in BALB/c MyD88-/-animals." (PMID 25954804, 2015).
infection (continued). "Infected DKO mice succumbed earlier than mice lacking MyD88 alone, while WT and CD40−/− mice survived the infection without signs of severe disease." (PMID 26441965, 2015). "GSEA revealed that genes from the MyD88-mediated pathways (P = 0.019) and IL-6, IL-10 and G-CSF cytokine pathways (P = 0.033) are highly enriched during HN878 infection when compared to non-infected samples." (PMID 25790379, 2015). "Unlike the RLRs, the role of specific signaling components downstream of TLRs including the adaptors MyD88 and TRIF (Toll/IL-1 receptor domain-containing adaptor inducing IFN-β) during infection has not been well studied in relevant cell types." (PMID 23359266, 2013). "Thirteen days after infection, mRNA expression of CCL3 and CCL7 in the spleens of MyD88−/− was increased by approximately 21 and 61 fold respectively over non-infected MyD88−/−." (PMID 23374751, 2013). "However, the absence of increase in viral burden observed at day 3 in mice lacking TLR2 indicates that other mechanisms dependent on MyD88 signaling may be involved in viral clearance since an increase in viral titers was observed in MyD88−/− mice at both 3 and 5 days post-infection." (PMID 21060793, 2010). "Confirming the absence of MyD88, we found that TNFα was not secreted by the MyD88−/− macrophages following infection as should be expected given that TNFα induction is entirely TLR2- and MyD88-dependent." (PMID 20041145, 2009). "Here, our aim is to further examine the role of MyD88 and TRIF in cAMP-induced CRH promoter activation in the absence of infection or TLR stimulation." (PMID 19615077, 2009). "Previously, we demonstrated that mice lacking both MyD88 and TRIF, in which TLR-dependent activation was abolished, are highly sensitive to infection with T. cruzi." (PMID 19609356, 2009). "Here we demonstrate that inhibition of MyD88 and TRIF signaling block cAMP-induced CRH promoter activation in the JEG3 cells in the absence of infection." (PMID 19615077, 2009). "We previously reported that MyD88−/− mice infected with C. pneumoniae fails to recruit PMN into the lungs during early and late stages of the infection." (PMID 19360122, 2009). "MyD88 and TRIF exert direct regulatory effect on cAMP-induced CRH promoter activation in JEG3 cells in the absence of infection." (PMID 19615077, 2009). "We conclude from these studies that TLR2 and MyD88, but not TLR4, play critical roles in the innate immune response to F. tularensis infection regardless of the route of infection or the subspecies." (PMID 19936231, 2009). "Theoretically, TLR agonists could compensate for the absence of key proteins in signaling pathways, such as MyD88 or IRAK-4, restoring a patient’s ability to fight infections." (PMID 41369391, 2025). "However, although IL-1β transcripts were induced by d7 post-infection, IL-1β treatment of fibroblasts did not reproduce the strong inhibition of HCMV spread we observed in MyD88-expressing cells." (PMID 40638072, 2025). "Unlike the invasion mechanisms of protozoans, during infection by the nematode A. cantonensis, an increase in Cav-1 expression in the brain and through the TLR4/MyD88 signaling pathway to activate MMP-9 leads to degradation of tight junction proteins (Zo-1 and claudin-5)." (PMID 38922036, 2024). "The inhibition of AdV-C5 infection with miR-29b-1* mimic depended on the IFN-alpha receptor 2 (IFNAR2) and the RNA-helicase retinoic acid-inducible gene I (RIG-I) but not cytoplasmic RNA sensors MDA5 and ZNFX1 or MyD88/TRIF adaptors." (PMID 35891387, 2022). "Together, these data identified a critical role for MyD88 in the induction of important pro- and anti-inflammatory cytokines in response to NMII infection in vitro, but also suggest that not all transcriptional responses in NMII-infected BMM require MyD88 signaling." (PMID 30800124, 2019).
infection (continued). "In contrast to the clear MyD88-dependence of these chemokines and IFNγ-response genes, the induction of the immunoregulatory cytokine IL-10 and of the enzyme Arginase-1 by NMII was largely independent of MyD88, which contrasts to the results obtained with BMM after infection with NMII in vitro." (PMID 30800124, 2019). "Moreover, the absence of signals mediated by MyD88, TLR2, or TLR4 reduced nitric oxide synthase 2 (Nos2) mRNA expression during infection." (PMID 30555476, 2018). "We first asked whether infection with another Gram-negative bacterium, A. baumanii (strain NM970), could lead to similarly dysregulated antibody production in MyD88−/− mice." (PMID 29973931, 2018). "However, after multiple infections, TLR4 and TLR9 levels showed no change, MyD88 was diminished even further and Nod1 and its main adaptor protein, Rip2, were elevated significantly." (PMID 28300841, 2017). "Together, these data suggest that MyD88-mediated signaling in CD11c+ MNP, but not MO alone, is critical and sufficient to activate the colonic ILC3 response, and to efficiently protect mice during the early phase of infection with C. rodentium." (PMID 28520792, 2017). "To further determine whether inflammasome activation can be rescued in infected MyD88-/- BMM by addition of IFNβ, we treated BMM from WT and MyD88-/- mice with or without IFNβ followed by IOE infection, and measured levels of IL-1β." (PMID 29049365, 2017). "We have demonstrated that the absence of MyD88 signaling impairs the establishment of the local inflammatory response induced by CLP, which results in a decline in neutrophil recruitment to the site of infection." (PMID 25084278, 2014). "Infection of human or murine pDCs with live WT VAC also fails to induce type I IFN production, whereas infection with heat-inactivated vaccinia (Heat-VAC, by incubating at 55°C for 1 h) induces TLR7/MyD88-dependent type I IFN production." (PMID 24743339, 2014). "However, unlike the MyD88−/− and IFN-γ−/− mice, which succumbed to infection, the NLRP3−/− and caspase-1−/− mice survived infection." (PMID 24098823, 2013). "Similarly, during the infection with Toxoplasma gondii, the TLR adaptor (MyD88) seems to be important for DC but not for macrophage activation evidencing the discrepancies in the use of TLRs in different cell subsets." (PMID 23650544, 2013). "However, TLR4−/− and MyD88−/− mice, and also wild-type, TLR2−/− and TRIF−/− mice, were refractory to infection when exposed to C. difficile without any prior antibiotic treatment (data not shown)." (PMID 21738466, 2011). "The Myd88−/− mice did not mount MIP-2 and neutrophil responses to CFT073 or ΔTcpC infection." (PMID 20886104, 2010). "At a later stage of infection, IL-1β, IFN-γ and other inflammatory mediators may be upregulated via a MyD88-independent pathway but are not sufficient to prevent mortality from C. pneumoniae." (PMID 21108806, 2010). "Furthermore, except for IL-12, 3d mice infected with T. gondii mounted a normal systemic pro-inflammatory response, while the MyD88/TRIF double knockouts did not, indicating that the immunological response to infection was fundamentally different." (PMID 20865117, 2010). "Similarly, Myd88 knockout mice failed to control F-MLV, and sustained high viral titers (107 foci/spleen) for several months after infection." (PMID 19214214, 2009). "Myd88−/−Trif−/− mice lacking TLR signaling showed normal T. cruzi-induced Th1 responses and maturation of dendritic cells (DCs), despite high sensitivity to the infection." (PMID 19609356, 2009). "Although the role of PMN recruitment and LPA formation clearly depends on DKK1, we considered the possibility that the deletion of MyD88 or the absence of DKK1 in platelets might also impact the infiltration of macrophages and dendritic cells to the infection site." (PMID 40502169, 2025).